ENSG00000251922
Synonyms: LOC124902573
Gene: Small nucleolar RNA gene on chromosome 10 (6,017,054 to 6,017,194, reverse strand). Ensembl gene ENSG00000251922.
Gene Ontology:
Biological process: RNA processing
Cellular component: nucleolus
Homologues: Orthologues: rat LOC120098679 (67% identical), mouse Gm26397 (67% identical). Paralogues in human: SNORA14B (70% identical), SNORA14A (67% identical).